ENSG00000277611 (novel protein)
Gene: Protein-coding gene on chromosome 20 (43,540,171 to 43,569,498, forward strand). Ensembl gene ENSG00000277611.
Genetic constraint (gnomAD): Missense variants: 79 observed, 101.47 expected, observed/expected ratio (o/e) 0.78, 90% interval 0.65 to 0.94. Synonymous variants: 39 observed, 40.53 expected, observed/expected ratio (o/e) 0.96, 90% interval 0.74 to 1.26.